BRCA1 (BRCA1 DNA repair associated)
Diseases named in the same sentence as BRCA1 in open-access papers (continued):
Sharing a sentence is not in itself a finding about the gene and the disease.
ovarian carcinoma (continued). "BRCA1/2 mutations are at the heart of homologous recombination repair deficiency (HRD) in ovarian cancer, and mismatch repair (MMR) detection in ovarian cancer is commonly associated with non-serous ovarian cancer and is often associated with Lynch syndrome." (PMID 39882448, 2024). "It is observed that this combination is more effective in patients with metastatic TNBC or prostate cancer carrying BRCA1/2 mutations or HRD, while the curative effect is similar between ovarian cancer patients with or without BRCA1/2 mutations or HRD." (PMID 37345194, 2023). "It is therefore important that patients with very early breast/ovarian cancer and congenital abnormalities, as well as patients with an FA-like phenotype (particularly in the absence of BMF), are screened for biallelic BRCA1 mutations." (PMID 38146508, 2023). "As BRCA1/2 carriers with epithelial ovarian cancer respond better to platinum-based chemotherapies than non-carriers, the BRCA1/2 status can be used to inform patients about their expected survival." (PMID 37296748, 2023). "BRCA1 methylated (BRCA1met) epithelial ovarian cancer (EOC) is a recently defined and not well-investigated subset of neoplasms." (PMID 37854675, 2023). "When comparing the GIS distributions of BRCA1/2-deficient samples, TNBC tumors were significantly different from ER + BC tumors (p < 0.001), but not significantly different from ovarian cancer tumors (p = 0.35)." (PMID 37589839, 2023). "Women diagnosed with non-mucinous high-grade epithelial ovarian cancer (EOC) in England are often reflex-tested for germline and tumour BRCA1/2 variants." (PMID 36765687, 2023). "A total of 281 samples were found to be CNV-negative, while 11 patients with ovarian cancer (No. 1–5, 7–12) and one patient with pancreatic cancer (No. 6) were identified to carry CNVs in BRCA1 or BRCA2 genes by MS assay." (PMID 38274092, 2023). "Apart from BRCA1, BRCA2 and MSH6, no clearly pathogenic variant was identified in other established ovarian cancer genes tested." (PMID 37013556, 2023). "Poly (ADP-ribose) polymerase (PARP) inhibitors are one of the most successful examples of clinical translation of targeted therapies in medical oncology, and this has been demonstrated by their effective management of BRCA1/BRCA2 mutant cancers, most notably in breast and ovarian cancers." (PMID 37190285, 2023). "Further, mutations in BRCA1 pose high risk for both breast and ovarian cancer, while BARD1 mutations are only a risk factor for breast, but not ovarian cancer." (PMID 36716349, 2023). "While germline BRCA1 or BRCA2 mutations have, until recently, been the only validated indications for PARPi-based therapy in breast and ovarian cancer, it has become clear that they were not the sole causes of an HRD phenotype." (PMID 37007122, 2023). "All BRCA1/2 carriers without previous history of breast or ovarian cancer are encouraged to participate in a specific preventive program and recommended to consider risk-reducing surgeries at the oncological institutions in the Czech Republic." (PMID 36831416, 2023). "Ovarian cancer, which is common to both path_MMR and path_BRCA1/2 carriers, and where both non-inherited MSI and path_BRCA1/2 associated cancers occur, is an example." (PMID 37821984, 2023). "A positive BRCA1/2 test is highly predictive of breast/ovarian cancer, but a negative test is not very predictive of not having these cancers." (PMID 36981032, 2023). "In our study, we addressed this issue at the homopolymeric regions of BRCA1/2 in a retrospectively selected cohort of 157 patients affected with high-grade ovarian cancer and negative at tumour testing by ION Torrent sequencing." (PMID 37179432, 2023). "While there are a few studies in the literature that explore hereditary ovarian cancer and gene mutations of BRCA1 and BRCA2, research specifically focusing on the prognostic factors of ovarian cancer has not been conducted in Cyprus." (PMID 38136256, 2023).
ovarian carcinoma (continued). "Our findings support the importance of HRD testing in ovarian cancer patients, demonstrating the potential therapeutic advantage of PARPi therapy in HRD-positive patients without somatic BRCA1/2 mutations." (PMID 37296748, 2023). "The status of BRCA1/2 can be used for counseling patients with expected survival because BRCA1/2 carriers with epithelial ovarian cancer respond better to platinum-based chemotherapy than non-carriers." (PMID 36611214, 2023). "CNVs analysis showed that 287 samples (including No. 7–12) were CNV-negative, while five patients with ovarian cancer (No. 1–5) and one patient (No. 6) with pancreatic cancer were identified to carry CNVs in BRCA1 or BRCA2 genes." (PMID 38274092, 2023). "The assembled dataset consisted of 10,373 ovarian cancer cases, including 2044 germline BRCA1 carriers, 761 germline BRCA2 carriers and 7568 non-carriers (based on germline testing)." (PMID 37076566, 2023). "A BRCA1/2 PV prevalence of 11.0% was identified in patients with mBC without a family history of breast and/or ovarian cancer." (PMID 35805063, 2022). "As expected, BRCA1 and BRCA2 PV rate nearly doubled in cases with a FH of PC nearly compared to sporadic subjects (3.6% vs. 1.7%), while it ranged from 1.7% to 15.8% in subjects with a personal or family history of breast/ovarian cancer." (PMID 36139606, 2022). "The prevalence of BRCA1/2 PVs was 11.0% in patients with mBC without a family history of breast and/or ovarian cancer." (PMID 35805063, 2022). "There are currently many custom/academic or commercial BRCA1/2 target panels that have been established in recent years because of investigations on the use and impact of NGS in breast/ovarian cancer, the majority of which are based on the amplicon sequencing technique." (PMID 36140751, 2022). "While the present study has limitations of small numbers of publications in certain subgroups, a relatively large number of publications with BRCA1/2m in breast and ovarian cancers were identified but not in other cancer types." (PMID 35909902, 2022). "We next analysed cervical samples from yet unaffected BRCA1 (n = 57) and BRCA2 (n = 53) mutation carriers (i.e. women who have not yet developed breast and/or ovarian cancer) and 114 healthy controls." (PMID 35105882, 2022). "Even BRCA1, which is obviously associated with the HRD phenotype in breast or ovarian cancer, does not necessarily undergo second-hit inactivation in pancreatic or prostate carcinomas." (PMID 36361916, 2022). "Olaparib has also been shown to induce both intratumoral and peripheral effector CD4+ and CD8+ T cells in ovarian cancer cells lacking Brca1." (PMID 36230543, 2022). ",17, 18, 19 Use of response to induction platinum-based therapy has consistently been used as a surrogate to enrich for PARP-sensitive ovarian cancer subpopulations irrespective of BRCA1 and BRCA2 status." (PMID 35990583, 2022). "When BRCA1 was knocked down, the mRNA and protein levels of ADRB1 in the three ovarian cancer cell lines increased compared with those in the control groups, indicating that BRCA1 knock-down induces ADRB1 expression in ovarian cancer cells." (PMID 35517499, 2022). "Among ovarian cancer patients, BRCA1 and especially BRCA2 carriers respond better than non-carriers to platinum-based chemotherapy and have prolonged survival." (PMID 35494038, 2022). "The NCCN guidelines suggest the recommended age for RRSO is 35–40 years for BRCA1 mutations and 40–45 years for BRCA2 mutations, because there is no effective surveillance for ovarian cancer." (PMID 35191009, 2022). "This is exemplified by PARPi used to treat breast, prostate, pancreatic or ovarian cancers with defects in the HR pathway, controlled by the tumour suppressors including (but not exclusive to) BRCA1, BRCA2, PALB2, RAD51C and RAD51D." (PMID 35567571, 2022).
ovarian carcinoma (continued). "Beyond BRCA1/2, HRD score calculated by the sum of LOH, TAI, LST scores was also identified as a biomarker since patients with high HRD scores were reported to respond well to PARPi treatment in breast and ovarian cancer." (PMID 35578198, 2022). "Triple negative breast (TNBC) and ovarian carcinomas (OvCas) with BRCA1 promoter methylation (BRCA1meth) respond more poorly to alkylating agents compared to those bearing mutations in BRCA1 and BRCA2 (BRCAmut)." (PMID 35857626, 2022). "In those families, the study consisted of 44 BRCA1 breast and/or ovarian cancer patients, 58 BRCA2 cancer patients, 602 non-BRCA patients and 328 other counselled patients." (PMID 35469032, 2022). "As the response to anti CTLA-4 and PARPis, the increase in local IFNγ is competent to prohibit tumor growth, while this drug combination does not have similar roles to BRCA1-sufficient ovarian cancer." (PMID 35281059, 2022). "BRCA1 and BRCA2 tumor analyses is done for all ovarian cancer patients." (PMID 35469032, 2022). "In this study ovarian cancer onset was 8–11 years earlier for BRCA1 patients compared to patients in BRCA2 and non-BRCA group." (PMID 35469032, 2022). "A large number of putative suppressor genes that are silenced or activated by aberrant methylation have been identified in ovarian cancer, including hypermethylation of OPCML, RASSF1, CDKN2B as well as classical tumor suppressors BRCA1, p16 and MLH1, and hypomethylation of LINE-1, SLC6A12 and PRAME." (PMID 35710397, 2022). "Mutations in BRCA1, BRCA2, RAD51C, and PALB2 genes were already shown to correlate with the risk of ovarian cancer, but not with BOTs." (PMID 35313928, 2022). "Therefore, we proposed a potential regulatory network between miR-9-5p and BRCA1 in the synergistic effects of Cur and PTX on ovarian cancer." (PMID 36703740, 2022). "UWB1.289, a BRCA1-null ovarian cancer cell line, displayed slightly higher basal PAR levels compared to UWB1.289+BRCA cells, which have restored BRCA1 function, perhaps reflecting greater reliance on PARP activity for DNA damage repair in the HR-deficient UWB1.289 parental cells." (PMID 35736348, 2022). "Numerous studies have focused on the cancer risks of BRCA1 and BRCA2, but increased attention is needed to the multitude of non-BRCA mutations that impart ovarian cancer risk." (PMID 35159349, 2022). "As known, 40% - 60% of BRCA1 and 11% - 27% of BRCA2 germline carriers develop ovarian cancer." (PMID 36531003, 2022). "These tumor forms were selected based on their association with BRCA1 germline pathogenic variants and previous findings of elevated BRCA1 methylation among individuals with a diagnosis of HGSOC but not among other ovarian cancers." (PMID 36074460, 2022). "Thus, our study demonstrates, for the first time, that ddPCR can be used for the accurate quantitation of BRCA1 and BRCA2 mRNA in FFPE ovarian cancer specimens." (PMID 35203410, 2022). "In high-grade ovarian cancer, tumors with alterations in BRCA1, but not BRCA2, for example, demonstrated a more immunoreactive phenotype characterized by higher levels of TILs." (PMID 36077694, 2022). "Thus, we focused on BRCA1 in subsequent experiments, and proposed that BRCA1 has opposite effects on the synergy of Cur and PTX in ovarian cancer when compared with miR-9-5p." (PMID 36703740, 2022). "We wanted to verify whether ovarian cancer cells express higher levels of ADRB1 and upon BRCA1 knock-down." (PMID 35517499, 2022). "Founder effects can also be detected in other non-neurologic conditions: BRCA1/2 variants [MIM: 113705, 600185] among Colombian women with breast and ovary cancer increased the prevalence of these variants in the studied population." (PMID 35260199, 2022). "BRCA1 and BRCA2 have key roles in the development of breast/ovarian cancer." (PMID 33726785, 2021).
ovarian carcinoma (continued). "Silencing of DDX11 using siRNA reduced cell viability in a series of ovarian cancer cell lines, namely UWB1.289 + BRCA1, OVCAR8, IGROV1, and COV362 as assessed by crystal violet staining of viable cells upon chronic cisplatin and olaparib drug treatment for 5 to 6 d." (PMID 33879618, 2021). "In addition, P300 is also a co-activator BRCA1, and it mediates histone acetylation at the sites of double strand DNA breaks thus facilitating DNA repair; its inhibition might therefore constitute another interesting strategy to sensitize ovarian cancer to the action of PARP inhibitors." (PMID 34439123, 2021). "For ovarian cancer patients with FIGO IIIB, IIIC, and IV, NAC-IDS did not adversely affect survival outcomes due to different BRCA1/2 germline mutational status." (PMID 35071013, 2021). "Several studies, including a large meta-analysis encompassing almost 8000 ovarian cancer cases, have reported that BRCA1 and BRCA2 carriers have better survival than non-carriers, but the survival advantage diminishes with time from diagnosis." (PMID 33670479, 2021). "LGR in the BRCA1/2 genes are present in a small percentage of patients with breast and ovarian cancers, but the method used in the present study does not allow them to be detected." (PMID 33918338, 2021). "To assess the functional role of PLA2G7/PAF-AH and its possible impact on the Wnt/β-catenin signaling pathway in ovarian cancer, we performed in vitro experiments in the BRCA1-negative ovarian cancer cell line UWB1.289." (PMID 34206491, 2021). "Unlike mutation carriers of BRCA1/2, ovarian cancer is not commonly seen in PABL2 mutation carriers; 26.6% of the BRCA1 developed personal ovarian cancer, while only 7.7% of PABL2 carriers developed ovarian cancer (p-value < 0.001)." (PMID 34439348, 2021). "This study estimated the prevalence of BRCA1 and BRCA2 PSVs among female patients ≥18 years of age that are diagnosed with ovarian cancer, peritoneal cancer, and fallopian tube cancer in the Gulf region, with the aim of informing clinical practice and improving clinical treatments in the future." (PMID 34930165, 2021). "Testing women for the panel of population-specific recurrent/founder mutations may be a valuable approach for therapy decisions in ovarian cancer patients (i.e., platinum or PARP inhibitors in BRCA1/2 carriers) or for preventing hereditary ovarian cancer." (PMID 33670479, 2021). "One report showed an AGCT in both a BRCA1 and a BRCA2 series of ovarian cancers." (PMID 34069790, 2021). "The highest increases of PARP1/ACTB mRNA ratios were induced by the most potent PARP inhibitor, the bilactamic steroid alkylator ASA-B, reaching at 120-fold increase in SKOV-3 and a 42–50-fold increase in UWB1.289, UWB1.289 + BRCA1 and OVCAR-3 human ovarian cancer cells." (PMID 34440232, 2021). "In women who harbour a pathogenic or likely pathogenic variant in BRCA1 and BRCA2 screening for ovarian cancer is not recommended." (PMID 34565426, 2021). "Then, only limited genetic screening was performed for highly recurrent P/LPVs in BRCA1 and BRCA2 detected in Slovenian HBOC families and extended genetic analysis was limited only to those with a substantial family history of breast and/or ovarian cancer." (PMID 33891299, 2021). "In the PCR, the expression of PAFR was significantly higher in the serous, BRCA-1 negative ovarian cancer cell lines (UWB1.289) compared to the other groups (p ≤ 0.0001)." (PMID 34571986, 2021). "While these guidelines incorporate decades of evidence for BRCA1 and BRCA2, guidelines are not as clear for other, less well-characterized genes associated with increased ovarian cancer risk." (PMID 33926482, 2021).
ovarian carcinoma (continued). "Although BRCA1 expression was significantly downregulated in 1-year cultures compared to that of 4-month cultures, the data show that the mechanism for this ovarian cancer model is not based on LOH." (PMID 34965417, 2021). "Therefore, we focus on BRCA1/2-related mechanisms of carcinogenesis for high-grade serous epithelial cancer (HGSC), as high-grade ovarian carcinomas are most likely to demonstrate the greatest benefit from PARPi therapeutics among ovarian cancers." (PMID 34070674, 2021). "In contrast, a recent study found that BRCA1/2 germline-related breast and ovarian cancers did not represent a unique phenotypic identity, but they express a range of phenotypes similar to sporadic cancers." (PMID 34202525, 2021). "The DNA methylation of BRCA1 and MGMT has been previously reported in ovarian cancer." (PMID 35008168, 2021). "The oncogenic features of miR-182 in ovarian cancer are noticeably due to impairment in double-strand breaks repair in DNA, negative control of BRCA1, suppression of metastasis suppressor 1 (MTSS1), and overexpression of high-mobility group AT-hook 2 (HMGA2)." (PMID 34721577, 2021). "For ovarian cancer, one of the studies showed no overall association between HRT and cancer risk in BRCA1/2 mutation carriers." (PMID 33885953, 2021). "The cumulative risks for both breast and ovarian cancer at OCCR were not higher than those at the other two BCCRs for both Korean BRCA1 and BRCA2 carriers." (PMID 34063308, 2021). "By in vitro expression analysis, a relevant gene and protein expression of PLA2G7/PAF-AH was detected exclusively in the BRCA1-negative ovarian cancer cell line UWB1.289 (p < 0.05)." (PMID 34206491, 2021). "As we did not have genetic data on variants in the BRCA1/BRCA2 genes predisposing for hereditary breast and ovarian cancer or the CDH1 gene predisposing for hereditary diffuse gastric cancer, we excluded these families from the FCCTX cohort." (PMID 32321466, 2020). "Taken together, the 3326A>T heterozygous mutation of BRCA1 gene and the 1342A>C heterozygous mutation of BRCA2 gene were detected in the confirmed II generation ovarian cancer patients, but none of those in healthy generation II was found." (PMID 32356124, 2020). "This study protocol describes a RCT evaluating structured decision support consisting of a decision aid and decision coaching for BRCA1/2-positive women with no prior history of breast or ovarian cancer." (PMID 32513307, 2020). "Furthermore, the expression level of BRCA1 was shown to be reduced due to depletion of the CDK12 kinase, which sensitizes breast and ovarian cancer cells to PARP inhibition." (PMID 32029455, 2020). "These women had no clear family history of breast/ovarian cancer but had an age of diagnosis similar to patients with germline BRCA1 alterations." (PMID 32719340, 2020). "As compared to previous streamlined studies with BRCA1 and BRCA2 testing in ovarian cancer patients only, in our study, genetic testing was performed using a multi-gene panel approach in patients with a personal history of breast and/or ovarian cancer." (PMID 32028617, 2020). "We found that BRCA1/2 germline related breast and ovarian cancers do not represent a unique phenotypic identity, but they express a range of phenotypes similar to sporadic cancers." (PMID 32164626, 2020). "A total of 52 unrelated women at-risk for HBOC and negative for BRCA1/BRCA2 pathogenic variants were evaluated through a gene panel comprising 14 breast and/or ovarian cancer susceptibility genes." (PMID 33134171, 2020).